GDF11 (growth differentiation factor 11)
Diseases named in the same sentence as GDF11 in open-access papers (continued):
Sharing a sentence is not in itself a finding about the gene and the disease.
thyroid (2 papers, 2019 to 2024). "Collectively, these data highlight a consistency between the genetic regulation of GDF11 and its associations with hypothyroidism, supporting the potential role of GDF11 in the development or progression of thyroid disease." (PMID 39237910, 2024). "Further research is needed to elucidate the role of GDF11 in metabolism and its potential involvement in thyroid pathophysiology." (PMID 31248139, 2019). "Furthermore, our results pointed to a relationship between GDF11 and thyroid phenotypes, particularly hypothyroidism." (PMID 39237910, 2024).
uveal melanoma (2 papers, 2019 to 2025). A melanoma derived from melanocytes of the uveal tract. "Firstly, we only explored the association between GDF11 expression in tumor tissues and the OS of uveal melanoma patients." (PMID 30883611, 2019). "High GDF11 expression was associated with uveal melanoma in advanced stages (IV), epithelioid cell dominant subtype, as well as extrascleral extension." (PMID 30883611, 2019). "The association between GDF11 expression and the clinicopathological parameters in patients with primary uveal melanoma in TCGA." (PMID 30883611, 2019). "In this study, by using data from TCGA-UVM, we demonstrated that high GDF11 expression was associated with uveal melanoma in advanced stages (IV), epithelioid cell dominant subtype, as well as extrascleral extension." (PMID 30883611, 2019). "To further explore the association between GDF11 expression and the phenotypes of uveal melanoma, we retrieved RNA-seq and clinicopathological data in TCGA-UVM." (PMID 30883611, 2019). "In this study, we aimed to assess the expression profile of GDF11, its prognostic value in terms of OS, as well as the potential mechanisms leading to its dysregulation in uveal melanoma." (PMID 30883611, 2019). "In this study, we explored the potential genetic and epigenetic (typically methylation) alterations in GDF11 DNA in uveal melanoma." (PMID 30883611, 2019). "Methylation modulated GDF11 expression might be a valuable prognostic biomarker in terms of OS in uveal melanoma." (PMID 30883611, 2019). "Since we identified that GDF11 expression might be a valuable prognostic indicator in uveal melanoma, we then tried to assess the potential mechanisms of its dysregulation." (PMID 30883611, 2019). "Based on these findings, we infer that methylation modulated GDF11 expression might be a valuable prognostic biomarker regarding OS in uveal melanoma." (PMID 30883611, 2019). "By examining GDF11 DNA CNAs in uveal melanoma, we found that DNA amplification and deletion were not frequent." (PMID 30883611, 2019). "Although another CpG site cg15466281 also showed a moderately negative correlation with GDF11 expression (Pearson’s r = -0.55), the average methylation of this site was low in uveal melanoma (mean ± SD: 0.04 ± 0.04)." (PMID 30883611, 2019).
acute coronary syndrome (1 paper, 2021). Signs and symptoms related to acute ischemia of the myocardium secondary to coronary artery disease. "Human plasma GDF11 levels were significantly lower in acute coronary syndrome patients than in chronic coronary syndrome patients." (PMID 34215721, 2021).
acute kidney injury (1 paper, 2016). Sudden and sustained deterioration of the kidney function characterized by decreased glomerular filtration rate, increased serum creatinine or oliguria. "Our study indicates that GDF11/8 in the kidney decreases with age and that GDF11 can increase tubular cell dedifferentiation and proliferation as well as improve tubular regeneration after acute kidney injury (AKI) in old mice." (PMID 27703192, 2016).
acute lymphoblastic leukemia (1 paper, 2025). Leukemia with an acute onset, characterized by the presence of lymphoblasts in the bone marrow and the peripheral blood. "In the present study, we aimed to determine the relevance of GDF11 in T-cell acute lymphoblastic leukemia-derived cells using Jurkat cells." (PMID 40746879, 2025).
allergies (1 paper, 2024). "The search did not reveal a robust relationship between MSTN variants and respiratory health, allergies, and immunity that was found for GDF11." (PMID 39237910, 2024). "Among the associations we identified with GDF11 variants, the largest portion (26.94%) were traits related to respiratory health, allergies, and immunity." (PMID 39237910, 2024).
amyotrophic lateral sclerosis (1 paper, 2019). Amyotrophic lateral sclerosis (ALS) is a neurodegenerative disease characterized by progressive muscular paralysis reflecting degeneration of motor neurons in the primary motor cortex, corticospinal tracts, brainstem and spinal cord. "In patients with amyotrophic lateral sclerosis (ALS), higher CSF levels of GDF11 were correlated with a better disease issue." (PMID 31330871, 2019).
aplastic anemia (1 paper, 2021). Anemia resulting from bone marrow failure (aplastic or hypoplastic bone marrow). "GDF11 levels are negatively correlated with hemoglobin levels in patients with aplastic anemia, suggesting a reduced response to GDF11 in these patients." (PMID 33886503, 2021). "Accordingly, the role of GDF11 in aplastic anemia requires further investigation." (PMID 33886503, 2021). "Significantly higher GDF11 levels have been observed in patients with aplastic anemia." (PMID 33886503, 2021).
asthma (1 paper, 2024). "PheWAS revealed robust associations between GDF11 cis-eQTLs and asthma, immune function, lung function, and thyroid health." (PMID 39237910, 2024). "Intriguingly, we found another GDF11 variant, rs1689510, exhibited significant associations with asthma, immune function, and lung function across multiple studies." (PMID 39237910, 2024). "Our analysis revealed that GDF11 variants and its predicted tissue-specific expression levels were consistently associated with asthma across multiple databases." (PMID 39237910, 2024). "Other traits associated with GDF11 expression in this category included “respiratory disease” (p = 1.30E-06, Z-score = -4.7), “self-reported asthma” (p = 3.17E-05, Z-score = -4.0), and “lung FEV1/FVC ratio” (p = 4.81E-05, Z-score = 3.9)." (PMID 39237910, 2024). "PheWAS of GDF11 cis-eQTLs revealed associations with asthma, lung function, immune function, and thyroid health, and PheWAS of broader GDF11 variants and TWAS of its predicted tissue-specific expression confirmed those findings." (PMID 39237910, 2024). "In addition to the presence of asthma, in our study, GDF11 variants and transcript levels were also associated with blood eosinophil counts." (PMID 39237910, 2024). "Additionally, we searched for associations with GDF11 variants in GeneATLAS and identified associations with respiratory disease, asthma, and hypothyroidism, validating our previous findings." (PMID 39237910, 2024). "Interestingly, phenome-wide association studies (PheWAS) of GDF11 tissue-specific cis-eQTLs revealed associations with asthma, immune function, lung function, and thyroid phenotypes." (PMID 39237910, 2024). "We propose that the associations identified within this study, linking GDF11 variants and transcript levels to respiratory and thyroid phenotypes—specifically asthma and hypothyroidism—are mediated through the involvement of GDF11 in inflammatory signaling pathways." (PMID 39237910, 2024). "Furthermore, PheWAS of GDF11 genetic variants confirmed these results, revealing similar associations with asthma, immune function, lung function, and thyroid health." (PMID 39237910, 2024). "We posit that GDF11 influences respiratory and thyroid health, particularly asthma and hypothyroidism, through its anti-inflammatory effects." (PMID 39237910, 2024). "Future research will expand our understanding of asthma genetics, including the relationship between GDF11, asthma, and the immune system." (PMID 39237910, 2024). "In this study, we report novel relationships between GDF11 and disease, namely asthma and hypothyroidism, in contrast to its formerly assumed role as a rejuvenating factor in basic aging and cardiovascular health." (PMID 39237910, 2024). "In this study, we provide evidence of GDF11 in the involvement of inflammatory diseases, namely asthma and hypothyroidism." (PMID 39237910, 2024).
bone metastasis (1 paper, 2022). Transfer of a neoplasm from its primary site to bones. "Upregulated GDF11 and CD151 expressions were positively correlated with bone metastasis, whilst the inverse correlation was shown with the other seven." (PMID 35685372, 2022).
breast tumours (1 paper, 2023). "Low expression of GDF9 was observed in breast tumours which developed bone metastasis in both TCGA and E-MTAB-4003 cohorts, whilst increased GDF11 expression was seen in those primary tumours which developed bone metastasis." (PMID 37333824, 2023).
cardiomyopathy (1 paper, 2024). A disease of the heart muscle or myocardium proper. "Our study findings suggest that cardiac-specific activation of GDF11 may offer a promising therapeutic approach for preventing cardiomyopathy in diabetic patients." (PMID 38715043, 2024).
chronic obstructive pulmonary disease (1 paper, 2024). A chronic and progressive lung disorder characterized by the loss of elasticity of the bronchial tree and the air sacs, destruction of the air sacs wall, thickening of the bronchial wall, and mucous accumulation in the bronchial tree. "Moreover, prior studies in humans with chronic obstructive pulmonary disease (COPD) report decreases in circulating GDF11 levels and reduced GDF11 expression in the serum and cells of these patients." (PMID 39237910, 2024).
dementia (1 paper, 2017). Loss of intellectual abilities interfering with an individual's social and occupational functions. "In the present study, high levels of circulating GDF-11 were detected in some participants with advanced age or dementia, and low levels of circulating GDF-11 were detected in some older subjects with MCI and healthy adults." (PMID 28611236, 2017).
diabetic retinopathy (1 paper, 2023). "GDF11 can alleviate the pathological progression of atherosclerosis, diabetic wounds, and diabetic retinopathy by improving endothelial cells dysfunction." (PMID 38143761, 2023). "GDF11 can alleviate the dysfunction of glucotoxicity-induced retinal microvascular endothelial cells in mice, thereby decreasing the progression of diabetic retinopathy." (PMID 38143761, 2023).
endothelial dysfunction (1 paper, 2021). In vascular diseases, endothelial dysfunction is a systemic pathological state of the endothelium (the inner lining of blood vessels) and can be broadly defined as an imbalance between vasodilating and vasoconstricting substances produced by (or acting on) the endothelium. "Furthermore, GDF11 also improves endothelial dysfunction, but there have been no studies to clarify the direct relationship between GDF11 and vascular endothelial cell aging and angiogenesis." (PMID 33728018, 2021).
Fibroadenoma (1 paper, 2024). A benign tumor of the breast characterized by the presence of stromal and epithelial elements. "Moreover, adenocarcinoma (MCF7) and fibroadenoma (MCF10A) cell lines exhibited lower GDF11 mRNA levels in MCF7 cells compared to MCF10A cells." (PMID 38611614, 2024). "In addition, immunofluorescence analysis of human adenocarcinoma revealed higher expressions of GDF11 in low-stage tumors (G1) compared to fibroadenomas." (PMID 38611614, 2024).
fibrosarcoma (1 paper, 2022). A malignant mesenchymal fibroblastic neoplasm affecting the soft tissue and bone. "Expression of the only growth factor coding gene in the top 25 most significant DEGs, GDF11, was also associated with fibrosarcomas." (PMID 36099287, 2022).
hypothyroidism (1 paper, 2024). Abnormally low levels of thyroid hormone. "Furthermore, the search revealed thyroid traits associated with GDF11 expression, such as “self-reported hypothyroidism” (p = 8.54E-06, Z-score = -4.3) and “hypothyroidism/myxodema” (p = 2.07E-05, Z-score = -4.1)." (PMID 39237910, 2024).
lung injury (1 paper, 2021). "Additionally, young MSCs-derived exosomes exceed their aged counterparts in alleviating lipopolysaccharride-induced acute lung injury, probably through the growth differentiation factor 11 (GDF11) largely recognized for its regenerative potential and tissue repair in different organs." (PMID 34059065, 2021).
muscular atrophy (1 paper, 2021). The loss of muscle tissue due to inactivity or disease. "Combined administration of a GDF11-neutralizing antibody with GYM329 in the muscular atrophy model diminished the superior effects of GYM329." (PMID 33495503, 2021).
muscular disease (1 paper, 2024). Myopathy is a peripheral nervous system disease consisting of any abnormal condition or disease of the muscular tissues; commonly designates a disorder involving skeletal muscle. "Prior studies had demonstrated roles for GDF11 in rejuvenating the aged heart, brain, and skeletal muscle, so we predicted that GDF11 variants would be associated with cardiovascular, cognitive, and muscular diseases and phenotypes." (PMID 39237910, 2024).
neuritis (1 paper, 2018). A neuropathy arising from inflammation of one or more nerves. "Cells without GDF11 treatment remained their native neural stem cell state (control), whereas cells treated with various concentrations of GDF11 showed visual outgrowth of neuritis, displaying phenotypes similar to neuron- and astrocyte-like cells (GDF11)." (PMID 30202652, 2018).
orofacial cleft (1 paper, 2024). A disorder of facial skeleton that is characterized by cleft lip and/or cleft palate that result in feeding, speech and hearing problems caused by failures during development. "This function of FST is further substantiated by exome sequencing-based studies revealing a mutant variant of FST that impedes interaction with GDF11, a TGF-β family member, resulting in orofacial clefts in human patients akin to FST-null mice." (PMID 38392348, 2024).
peripheral nerve injury (1 paper, 2024). Injury to a peripheral nerve. "Studies on the exogenous use of GDF-11 in peripheral nerve injury should be increased." (PMID 38248323, 2024).
prostate carcinoma (1 paper, 2023). A carcinoma that arises from epithelial cells of the prostate gland. "When lytic‐ and blastic‐like human prostate cancer cell are grown alone (potentially requiring a true microenvironment) in tissue culture they do not display any significant BMP ligand gene expression changes between these groups apart from GDF11 elevated in the blastic‐like cells." (PMID 36054271, 2023).
prostate tumor (1 paper, 2022). "Studies in prostate tumor have contented a unidirectional movement of GDF11 protein from tumor to circulation to muscle." (PMID 35524286, 2022).
Rett syndrome (1 paper, 2023). A severe neurodevelopmental disorder affecting the central nervous system.
rhabdomyosarcoma (1 paper, 2019). A rare aggressive malignant mesenchymal neoplasm arising from skeletal muscle. "In a reporter-gene assay conducted with a human rhabdomyosarcoma (A204) cell line, ACE-083 inhibited signaling by activin A, activin B, myostatin and GDF11 in a dose-dependent manner, with IC50 values ranging from approximately 40–700 pM or, in alternative units, 5–80 ng/mL." (PMID 31388039, 2019).
schizophrenia (1 paper, 2020). A major psychotic disorder characterized by abnormalities in the perception or expression of reality. "Schizophrenia is linked with abnormal neurodevelopment, on which growth differentiation factor 11 (GDF-11) has a great impact." (PMID 33364986, 2020). "For all we know, this study is the first to show that GDF-11 is associated with the psychopathology and cognition in schizophrenia." (PMID 33364986, 2020). "In this study, we verified this hypothesis by examining whether (i) plasma GDF-11 level was changed in schizophrenia patients and (ii) there was any association between GDF-11 level and both psychopathological and cognitive symptoms in these patients." (PMID 33364986, 2020). "In view of the vital regulatory role of GDF-11 in normal brain neural development and disrupted brain development in schizophrenia, we hypothesized that abnormal GDF-11 signaling might be implicated with the pathophysiology of schizophrenia." (PMID 33364986, 2020). "Recent studies have suggested that GDF-11 might be implicated in the pathogenesis of schizophrenia." (PMID 33364986, 2020). "The current study aimed to investigate the relationship between plasma GDF-11 levels and both psychopathological symptoms and cognitive function in schizophrenia." (PMID 33364986, 2020). "In this study, we showed a significant decrease in plasma GDF-11 level in schizophrenia, and decreased GDF-11 was correlated with the psychopathology and cognitive function of patients." (PMID 33364986, 2020). "We found that plasma levels of GDF-11 were significantly lower in schizophrenia patients relative to healthy controls." (PMID 33364986, 2020). "Furthermore, the exact mechanism of the decrease in GDF-11 levels in patients with schizophrenia is unclear, requiring further study." (PMID 33364986, 2020). "However, it should be noted that the difference in plasma GDF-11 levels between the patient and control groups could result from schizophrenia itself or other potential influence factors, such as the effect of antipsychotics." (PMID 33364986, 2020). "Many studies could support the presumption that decrease of GDF-11 in schizophrenia might not be just an incidental phenomenon, but be associated to the pathological mechanisms of schizophrenia." (PMID 33364986, 2020). "In combination with the roles of GDF-11 in neurogenesis and brain function and the effects of GDF-11 on nerve development and cell regulations, it is indicated that GDF-11 may be related to the pathophysiology of schizophrenia." (PMID 33364986, 2020). "However, a direct evidence linking GDF-11 to the pathophysiology of schizophrenia is still lacking." (PMID 33364986, 2020).
Sepsis (1 paper, 2025). Sepsis is defined as life-threatening organ dysfunction caused by a dysregulated host response to infection. "The overexpression of growth differentiation factor 11 (GDF11) further inhibits ferroptosis by promoting the activity of SIRT1, providing a new molecular target and therapeutic strategy for treating sepsis related ALI." (PMID 40109363, 2025).
skin aging (1 paper, 2019). The gradual irreversible changes in structure of skin that occur as a result of the passage of time.. "This study examined the impact of GDF11 on human skin, specifically related to skin aging." (PMID 31181098, 2019).
Splenomegaly (1 paper, 2019). Abnormal increased size of the spleen. "GDF11 is known to negatively affect erythrocyte maturation, and its blockade by ACVR2B-Fc increases extramedullary hematopoiesis leading to splenomegaly." (PMID 30765322, 2019).
steatosis (1 paper, 2020). Increased lipid within the cytoplasm of cells. "These pro-fibrogenic effects in vitro were accompanied by the absence of modulation of steatosis upon administration of GDF11 for 1-2 weeks either to wild type mice or to genetically obese ob/ob mice, respectively." (PMID 33126224, 2020).
thyrotoxicosis (1 paper, 2019). A hypermetabolic syndrome caused by the elevation of thyroid hormone levels in the serum. "Alternatively, it can be speculated that the muscle dysfunction observed with thyrotoxicosis may be in relation with a deficient response in GDF11 secretion." (PMID 31248139, 2019).